STAT3 (signal transducer and activator of transcription 3)
Diseases named in the same sentence as STAT3 in open-access papers (continued):
Sharing a sentence is not in itself a finding about the gene and the disease.
Cachexia (continued). "As a consequence, prevention of IL-6 activity by specific neutralizing antibodies or STAT3 inhibitors may represent another potential research area of new therapeutic agents to prevent lipolysis, brown adipocyte conversion, and cancer-associated cachexia." (PMID 40227577, 2025). "However, whether STAT3 is also implicated in the occurrence of cachexia in mouse models characterized by the formation of LM CRC needs to be determined." (PMID 31915140, 2020). "Moreover, this experimental work narrowly focused on known prognosticators associated with cachexia and, though STAT3 was found to be important in mediating HCT116-induced atrophy, it may not be the sole contributor to muscle wasting in contexts of cancer." (PMID 31915140, 2020). "Thus, cancer induced ER-stress markers in the liver, however cachexia progression further deteriorated liver ER-stress, disrupted protein synthesis regulation and caused a differential inflammatory response related to STAT-3 and NF-κB (Nuclear factor—κB) signaling." (PMID 25789991, 2015). "Its multifaceted involvement makes it difficult to delineate the exact mechanisms by which STAT3 contributes to cachexia and to develop therapies that selectively disrupt its pathological actions." (PMID 40704145, 2025). "Agents such as ruxolitinib and INCB018424 have shown preclinical efficacy in mitigating cachexia symptoms by suppressing STAT3 phosphorylation, normalizing cytokine/adipokine profiles, and reducing tissue wasting." (PMID 40704145, 2025). "Other IL-6 family cytokines, including oncostatin M (OSM) and leukemia inhibitory factor (LIF), also contribute to cachexia through STAT3 activation." (PMID 40704145, 2025). "Given its central role in cachexia pathogenesis, therapeutic targeting of the STAT3 pathway through small molecule inhibitors, monoclonal antibodies, or combination therapies presents a promising avenue for symptom management and improved patient outcomes." (PMID 40704145, 2025). "Pharmacological blockade of the JAK/STAT3 pathway has been shown to reduce muscle atrophy in C26‐driven cachexia, suggesting a significant role for this pathway in IL‐6/gp130‐mediated cachexia." (PMID 39764565, 2025). "Recent studies have illuminated the cross-talk between STAT3 and other signaling pathways that exacerbate cachexia-related metabolic imbalances." (PMID 40704145, 2025). "Our two knockout approaches—whole‐body Il‐6−/− and Li‐Stat3−/−—reveal the liver to be a novel target for IL‐6 signalling in cachexia." (PMID 38632714, 2024). "The prototype of cachexia triggered by IL-6 showed that skeletal muscle atrophy was prevented by blocking JAK/STAT3 signaling." (PMID 39404384, 2024). "It is reported that via directing the inflammatory response, the cachexia is significantly influenced by IL-6/JAK/STAT3 signaling." (PMID 39404384, 2024). "Together, these data indicate that RK prevents severe tissue atrophy in C26‐induced cachexia by reducing circulating IL‐6 concentrations and STAT3 signalling." (PMID 38302863, 2024). "In a similar way, pSTAT3 strongly bound Erfe promoter in atrophic muscles, indicating that activated STAT3 can be responsible for the upregulation of the BMP scavenger Erfe in cachexia." (PMID 38052214, 2023). "They showed that this co-culture led to muscle atrophy, associated elevations in cachexia markers, activation of the mTOR/AKT pathway in a time dependent manner, and activation of the STAT3 signalling pathway through EV transfer of PA1." (PMID 37798728, 2023). "The IL-6/JAK/STAT3 signaling has been found to have an important role in cachexia progression by regulating the inflammatory response." (PMID 37217930, 2023). "The crucial dependence of the CHX207 model on IL‐6 renders it suitable for studying the efficacy of STAT3 inhibitors (e.g. sorafenib), IL‐6‐, or IL‐6 receptor blocking antibodies (e.g. tocilizumab) to prevent fibrosarcoma‐induced cachexia." (PMID 36351437, 2023).
Cachexia (continued). "Fibrinogen concentration increases as severity of cachexia increases and a mechanism of STAT3 increasing fibrinogen synthesis through proteolysis resulting in cachexia has been proposed." (PMID 38022578, 2023). "Similar to STAT3 pharmacological treatment, the genetically-based STAT3 silencing in myeloid compartment controlled the weight loss, limiting CRS-associated cachexia." (PMID 34518653, 2022). "Combined, our results demonstrate how the IL-6 family of cytokines diverge from β-adrenergic signals by employing JAK/STAT3-driven transcriptional changes to promote adipocyte ATGL/CGI-58-dependent lipolysis contributing to adipose wasting in cancer cachexia." (PMID 35785158, 2022). "The IL-6-mediated activation of STAT3 is a common feature in muscle wasting in both cell culture models, as well as in C26 cancer cachexia mouse model." (PMID 36077789, 2022). "Finally, use of CRISPR/Cas9 techniques in pre-adipocytes confirmed the requirement of STAT3 in transmitting cachexia-associated, cytokine-induced lipolysis signals and validated this tool to further elucidate other molecules necessary for permitting cachexia-associated adipose wasting." (PMID 35785158, 2022). "MuRF-1 and atrogin-1 protein levels were upregulated in two cachexia cell line models, which was accompanied by increased STAT3 pathway activation and MHC downregulation." (PMID 36230949, 2022). "Our results demonstrated that the protein levels of atrogin-1, MuRF-1, myostatin, and p-STAT3 were higher in the cachexia group than in the NC group." (PMID 36230949, 2022). "Other pathways which were previously reported in cachexia such as IL-6 signaling, STAT3 signaling, protein ubiquitination pathway and mitochondrial dysfunction were also identified." (PMID 33334063, 2020). "In vivo studies show a pro-catabolic effect of STAT3 on skeletal muscles in experimentally induced cachexia." (PMID 33158194, 2020). "Our prediction analyses also revealed microRNA miR-17 as an important regulator of transcripts, such as Cxcl12, Mef2c, Stat3, and Cav1, that are translated into proteins with a role in cancer cachexia." (PMID 31013615, 2019). "In cachexia experimental models, STAT3 expression is induced and correlates with increased expression of skeletal muscle ubiquitin E3 ligases." (PMID 31114509, 2019). "We know also that other mediators belonging to the IL-6 superfamily, including IL-11 and OSM are present in the serum of animals with burn-induced cachexia and can activate the STAT3 signaling system in muscle." (PMID 31447786, 2019). "Our results identify the inhibition of eIF4A-responsive transcripts, such as STAT3, as a viable approach to alleviate cachexia." (PMID 29849089, 2018). "It has been established in various mouse models of cachexia that IL-6 catabolic signaling in cachexia is exerted through the transcription factor STAT3." (PMID 30081609, 2018). "Recent experiments in the C26 cachexia mouse model using anabolic androgen therapy in combination with HDAC inhibitor AR-42 was shown to block STAT3 mediated muscle atrophy." (PMID 30081609, 2018). "A majority of compounds that show inhibitory activity toward STAT3 activation also reduced markers of cachexia in cell culture models." (PMID 30081609, 2018). "Overall, these findings show that pharmacological inhibition of STAT3 activity mirrors the results obtained with genetic targeting of STAT3 and support the concept that STAT3 is a valid target for cachexia treatment." (PMID 30081609, 2018). "Other modalities of STAT3 inhibition have also been investigated in cachexia with promising results." (PMID 30081609, 2018). "Our results therefore indicate that targeting eIF4A reduces the abundance of multiple proteins, including iNOS, STAT3 and IL-6, which are essential in the onset of cachexia." (PMID 29849089, 2018).
Cachexia (continued). "Several known STAT3 inhibitors, designed to directly target hyper-phosphorylated STAT3 in cells, have been used as chemical probes to corroborate genetic experiments that highlight the role of STAT3 in cachexia." (PMID 30081609, 2018). "Our findings bolster the potential of eIF4A-inhibitors in the treatment of cachexia and other pro-inflammatory diseases driven by STAT3 or iNOS." (PMID 29849089, 2018). "The IL6/STAT3 pathway is thought to induce muscle wasting in cachexia experimental models via two routes." (PMID 30072615, 2018). "This review will discuss the implications for IL-6-induced STAT3 signaling in the regulation of cachexia-induced mitochondrial dysfunction." (PMID 28785374, 2017). "Activation of STAT3 signaling, a downstream mediator of the IL-6 family of cytokines signaling, can disrupt muscle protein turnover during cachexia." (PMID 27449092, 2016). "While enhanced muscle STAT3 activity corresponds to the suppression of protein synthesis, liver protein synthesis is elevated during the progression of cachexia and can promote hepatomegaly in cachectic mice." (PMID 27449092, 2016). "Previous reports demonstrated that STAT3 activation induced by IL-6 is per se sufficient to induce muscle fiber wasting in vitro as well as in vivo and that STAT3 inhibition would abolish skeletal muscle wasting downstream of IL-6 in cancer cachexia models." (PMID 25460504, 2015). "Among the mechanisms, we herein show that sunitinib is able to restrain the overactivation of STAT3 and MuRF-1 pathways, involved in enhanced muscle protein catabolism during cancer cachexia." (PMID 25460504, 2015). "More specifically, Cebpb is necessary for muscle wasting during LLC-induced cancer cachexia, Stat3 for muscle wasting during C26 cancer cachexia, and Fos for denervation-induced muscle loss." (PMID 25539728, 2014). "In the present study we chose to evaluate the relationship between the different cachexia definitions, systemic inflammation (serum C-reactive protein) and potential inflammatory signalling pathways within muscle (phospho-STAT3 and phospho-NFkB)." (PMID 24404136, 2014). "Of the top 20 Broad MSigDB canonical pathways up-regulated in both moderate and severe colon-26 cachexia, eight were related to inflammation, including the complement and coagulation pathways, IL-6, STAT3, JAK-STAT, cytokine and Toll-like receptor pathways." (PMID 21799891, 2011). "Microarray results were confirmed by qPCR and demonstrated robust induction of STAT3, C/EBPδ and acute phase response genes in moderate and severe cachexia." (PMID 21799891, 2011). "Among the known STAT3 targets increased in quadriceps in moderate and severe cachexia were STAT3 itself and the transcription factor CCAAT/enhancer-binding protein δ (C/EBP δ)." (PMID 21799891, 2011). "Notably, STAT3 activity correlates with cachexia severity in mouse models overexpressing TGF-β1 in skeletal muscle, further emphasizing this pathological axis." (PMID 40704145, 2025). "Additionally, the TME is intimately involved in STAT3-driven cachexia, as STAT3 regulates immune cell polarization, cytokine production, and metabolic crosstalk between tumor and host tissues." (PMID 40704145, 2025). "Notably, activation of PPARγ has been shown to reduce phosphorylation of NF−κB and STAT3 both in vitro and in vivo, thereby disrupting the chronic inflammatory feedback loop that sustains cachexia progression." (PMID 41476922, 2025). "STAT3 activation drives lipolysis and systemic metabolic imbalance by promoting the breakdown of triglycerides and impairing lipid storage mechanisms, thereby exacerbating energy depletion characteristic of cachexia." (PMID 40704145, 2025). "It has been reported that the activation of STAT3 signaling supports lipase ATGL and its co-activator CGI-58 dependent adipocyte lipolysis and increases serum leptin levels that may influence cachexia-associated anorexia." (PMID 38245529, 2024).
Cachexia (continued). "Moreover, it was demonstrated that the IL-6 family of cytokines required JAK/STAT3-dependent transcriptional changes to induce adipocyte lipolysis during cachexia." (PMID 37481560, 2023). "Blocking JAK/STAT3 signaling inhibited skeletal muscle wasting in an IL-6-induced cachexia model." (PMID 37217930, 2023). "However, here, we found a lower abundance of STAT3, whereas STAT3 inhibition has been shown to abrogate skeletal muscle wasting in cancer cachexia models." (PMID 35563153, 2022). "The expression of atrogin-1, MuRF-1, myostatin, and p-STAT3 was significantly reduced by the 2-DG treatment and prevented the transcriptional activation of MuRF-1 and atrogin-1, which was markedly increased in the cachexia group." (PMID 36230949, 2022). "Having established a strong association between STAT3-dependent cachexia-inducing cytokines in the RM9 system, we subsequently evaluated the effect of ruxolitinib and/or propranolol treatment in the RM9 in vivo cachexia model." (PMID 35785158, 2022). "A recent finding showed that the STAT3/HSP90/FOXO1 axis plays a role in muscle wasting in cachexia." (PMID 36077789, 2022). "Importantly STAT3 is a critical regulator of satellite cell self-renewal and this signaling component plays an important role in muscle wasting, including cachexia." (PMID 34829914, 2021). "Overall, this study clearly demonstrated that formation of HCT116 tumors contributes to the pathogenesis of cachexia in mice, and that LM in CRC exacerbate cachexia, as also supported by the molecular changes consistent with muscle atrophy (e.g. elevated phospho-STAT3, E3 ligases, ubiquitin)." (PMID 31915140, 2020). "Furthermore, IL-6 trans-signaling/STAT3 axis was identified as a therapeutic target in advanced cancer patients presenting cachexia." (PMID 31114509, 2019). "This antibody also suppressed the IL-6 activation of muscle STAT3 and FIS-1 protein expression during cachexia, suggesting that the intracellular IL-6 signaling targets such as STAT3 may contribute to the regulation of mitochondrial fission." (PMID 30918582, 2019). "Several known STAT3 inhibitors that directly target hyperphosphorylated STAT3 also reduced markers of cachexia in cell culture models and antagonized catabolic signaling in mice, supporting the concept that STAT3 is a valid target for cachexia treatment." (PMID 31569642, 2019). "In the present study, ajoene extract from crushed garlic (Allium sativum) ameliorates muscle atrophy by down-regulating not only myokines secretion but JAK/STAT3 and SMADs/FoxO signaling pathways, contributing to the preservation of muscle mass in a mouse model of cancer-induced cachexia." (PMID 31717643, 2019). "Available data identify STAT3 as a target for cachexia intervention." (PMID 30081609, 2018). "In vivo evidence of the specific involvement of IL6/STAT3 in causing cachexia-associated muscle wasting is that ApcMin/+ mice lacking IL6 do not develop cachexia." (PMID 30072615, 2018). "Insights into how STAT3 activation leads to protein degradation in cachexia came from studies that looked into the effects of catabolic conditions such as CKD and streptozotozin-induced acute diabetes on muscle metabolism in muscle-specific STAT3 knock out mouse." (PMID 30081609, 2018). "Indeed, multiple groups have found that STAT3 activation and protein levels correlates with serum IL-6 levels in cachexia murine models as well as patients." (PMID 29849089, 2018). "Taken together, this work demonstrates that different pro‐cachectic inducers (i.e. IL‐6 and IFNγ/TNFα) activate STAT3 signaling independently and that this signaling can collaborate with the NF‐κB pathway to induce cachexia through activation of target genes, like iNOS." (PMID 28264935, 2017). "Hepatic STAT-3 phosphorylation, however, is also considered to be an inflammatory marker and is sufficient to induce an IL-6 dependent muscle atrophy in the ApcMin/+ mouse with cachexia progression." (PMID 25789991, 2015).
Cachexia (continued). "Thus, the therapeutic potential of STAT3 inhibitors deserves to be tested in clinical trials of cachexia-related patients, and the identification of relevant signaling pathways related to STAT3 activation and downstream targets remains to be explored in the future." (PMID 37217930, 2023). "Finally, administration of JAK but not β-adrenergic inhibitors suppressed adipose STAT3 phosphorylation and associated adipose wasting in a murine model of cancer cachexia characterized by increased systemic IL-6 family cytokine levels." (PMID 35785158, 2022). "Integrated miRNA and mRNA co-profiles during skeletal muscle wasting in cancer-induced cachexia showed that extracellular matrix (ECM) associated genes are post-transcriptionally regulated by miRNAs (such as miR-29a-3p) and atrophy-related transcription factors including NF-κB, STAT3 and FOXO." (PMID 36077789, 2022). "However, BGM could effectively downregulate the STAT3, Akt, and FoxO4 phosphorylation despite the occurrence of CM-induced cachexia." (PMID 33802674, 2021). "Collectively, these results suggested that overexpression and hyper‐stimulation of RAGE induced by high S100B might trigger muscle atrophy via a p38 MAPK/myogenin axis and STAT3‐dependent MyoD degradation, possibly amplifying the activity of cachexia‐inducing cytokines." (PMID 32159297, 2020). "Therefore, dietary management involving supplementation of natural STAT3 inhibitors may help prevent alleviating changes during the development of cachexia in skeletal muscles." (PMID 33158194, 2020). "Moreover, it has been reported that cancer patients who exhibit cachexia may benefit from STAT3 inactivation, as it preserves fat and tissue mass and rescues cachectic phenotypes, in addition to eliminating tumors." (PMID 31569642, 2019). "Therefore, it still remains a subject of further study whether STAT3 actually promotes adipose tissue browning in cachexia and, if so, what mechanisms are involved." (PMID 30081609, 2018). "LIF promotes hepatic metabolic dysfunction via STAT3, and liver-specific deletion of the LIF receptor ameliorates cachexia-related lipid abnormalities." (PMID 40704145, 2025). "Increased levels of STAT3 phosphorylation, C/EBPδ, and myostatin were observed in the Lewis lung carcinoma (LLC) tumor-induced cachexia mouse model." (PMID 37217930, 2023). "Our results showed that PAI-1 is absorbed into the skeletal muscle cytoplasm and intracellular PAI-1 results in activation of STAT3 phosphorylation, leading to increased muscle atrophy and decreased muscle protein synthesis, thereby resulting in GBM cachexia." (PMID 36231065, 2022). "In line with previously published data, C26 secreted factors induced STAT3 phosphorylation under both plating conditions, indicating an important role for STAT signaling in C26 cachexia." (PMID 34395422, 2021). "Of note, STAT3 and CEPBδ are among the differentially expressed ATF‐1 target genes induced by cachexia that respond only to AR‐42 treatment." (PMID 31930715, 2020). "IL-6 can induce skeletal muscle signal transducer and activator of transcription 3 (STAT3) and extracellular regulated kinase (ERK1/2) in several preclinical cancer cachexia models." (PMID 30918582, 2019). "All in all, these findings highlight the therapeutic potential of structured exercise interventions in modulating STAT3 activity, offering a promising, non-pharmacological strategy to ameliorate muscle wasting and improve clinical outcomes in cancer cachexia." (PMID 40704145, 2025). "Interleukin (IL)-6 in LLC-exosomes induced the lipidolysis of 3T3-L1 adipocytes by activating the signal transducer and activator of transcription 3 (STAT3) and promoting the cachexia process and the neutralization of extracellular IL-6 prevented the lipolysis effects of LLC-exosomes." (PMID 38689293, 2024).